MED12 (mediator complex subunit 12)
Diseases named in the same sentence as MED12 in open-access papers (continued):
Sharing a sentence is not in itself a finding about the gene and the disease.
cancer (69 papers, 2012 to 2025). A tumor composed of atypical neoplastic, often pleomorphic cells that invade other tissues. "Overall, these results indicate that MED12 mutations impact multiple cancer-related biological processes in NSCLC, particularly immune responses and transcriptional regulation." (PMID 40888963, 2025). "Both genes are killer cell receptors expressed in immune cells, while MED12 mutation occurs only in cancer cells." (PMID 40888963, 2025). "MED12, a protein originally associated with transcriptional regulation, is critical in drug response modulation in various types of cancer." (PMID 40833497, 2025). "MED12 is involved in regulating essential steps of transcription, and its deregulation was linked to human cancers, while NFKB1 plays a role in macrophage polarization and innate immune memory responses." (PMID 39639867, 2024). "In this study, clinical and whole-exome sequencing (WES) data from published studies were merged as a WES cohort to explore the association between MED12 mutation (MED12-Mut) and ICIs efficiency across cancers." (PMID 36309740, 2022). "This TMPRSS2-ERG positive case had a somatic missense mutation in MED12 (c.3670C > G; p.Leu1224Val), that is potentially pathogenic in many cancers, including prostate, via its upregulation of Wnt/β-catenin signalling." (PMID 32392735, 2020). "MED12 mutations are currently perceived as a founder genetic event in PTs, but are significantly more prevalent in benign than in malignant tumors." (PMID 28267263, 2017). "Significant mutation frequency also implies that MED12 should be recognized as an important cancer gene in CLL." (PMID 25595892, 2015). "Our results recognize CLL as the first extrauterine cancer type where the 5′ terminus of MED12 is mutated at significant frequency." (PMID 25595892, 2015). "Our results recognize CLL as the first extrauterine cancer type where 5′ terminus of MED12 is mutated at significant frequency." (PMID 25595892, 2015). "Mutations of MED12 confer resistance to multiple anti-cancer therapies including conventional chemo and targeted therapies." (PMID 25277175, 2014). "Furthermore, pan-cancer analyses using all samples in the MSKCC dataset originating from 11 cancer types (N = 1661) also revealed that MED12-mutated cancers had a significantly longer survival period." (PMID 40888963, 2025). "One study suggests that the tumorigenic mechanisms associated with MED12 mutations may be cancer‐specific." (PMID 38379333, 2024). "Importantly, MED12 inhibition has been found to confer resistance to a number of anti-cancer drugs in the context of specific mutations that are normally targetable." (PMID 35326717, 2022). "This suggests that MED12 mutations contribute to the growth of malignant tumors." (PMID 34440096, 2021). "In addition, recent studies revealed frequent mutations in MED12, exon 2, in both benign and malignant tumors." (PMID 30832348, 2019). "The expression levels of 44 genes involved in various cellular and molecular phenomena associated with tumorigenesis, as well as genes involved in various steps of the MED12 signaling pathway in human embryogenesis and other types of MED12-associated cancers reported in the literature were assessed." (PMID 27806318, 2016). "In addition, these genes are prominently linked to “cancer” and “genetic disorders” (including “psychological disorders”), consistent with the established roles of MED12 as a both cancer driver and a XLID gene." (PMID 27188461, 2016). "This is the first MED12 mutation shown to lead to exon skipping in cancer." (PMID 27602765, 2016). "Array-CGH data show that the inhibition of MED12 expression is associated with malignant tumors." (PMID 22768200, 2012). "However, the details of molecular regulation between mutations and growth, as well as changes in chromatin status and cancer caused by MED12 mutations, remain unclear, and future studies are expected." (PMID 34440096, 2021).
cancer (continued). "It has been reported that MED12 functions in maintaining cancer cell proliferation, along with BRD4." (PMID 40888963, 2025). "We confirmed that the two MED12 KO cell lines were resistant to ceritinib and osimertinib, but trametinib exhibited strong anti-cancer effects in both cell lines." (PMID 40833497, 2025). "Collectively, these studies demonstrate that MED12 alterations, both transcriptionally and post-translationally, play a dual role in modulating chemotherapeutic response in various forms of cancer." (PMID 40833497, 2025). "In cancer cell lines, Med12 has been described to inhibit TGF-β signaling, an important pathway implicated in regeneration." (PMID 38742628, 2024). "While most of the core subunits of Mediator are pan-essential dependencies across all cancer cell lines, MED12 exhibits a high degree of cell line selectivity in its essentiality requirement." (PMID 37961243, 2023). "Arginine methylation of MED12 has been validated to modulate MED12-mediated transcriptional regulation and response to chemotherapy drugs in human cancer cell lines." (PMID 37771430, 2023). "MED12 is involved in transcription initiation and has been demonstrated to control drug responses in a variety of cancers." (PMID 36495130, 2023). "Mediator complex subunit 12 (MED12) has been reported as a potential biomarker of cancer and is a constituent of the CDK8 complex, which is involved in RNA pol II-mediated transcription." (PMID 36430260, 2022). "Methylation of MED12 renders cancer cells sensitive to chemotherapy drugs under in vitro and in vivo conditions, and higher levels of MED12 and CARM1 correlate with a better response to chemotherapy drugs." (PMID 34006904, 2021). "The results showed that ATM, CHD4, FAT1, KMT2D, MED12, NF2, and SUFU were the most frequently mutated cancer-related genes." (PMID 33193598, 2020). "Knockdown of MED12 in cancer cells led to an apparent cell proliferation defect by arrested cell cycle at G0/G1 phase." (PMID 31072327, 2019). "In the setting of the MED12-mutant pathway, borderline and malignant PTs might stem from a pre-existing FA and progress to a malignant phenotype following the acquisition of additional genetic alterations in cancer genes, including TERT promoter mutations and TERT amplification." (PMID 29043292, 2017). "Among those, MED12, CDX2, MLL and MLL3 are cancer census genes, which are found frequently mutated in other cancers (COSMIC)." (PMID 28256603, 2017). "This is in line with recent results showing that MED12 repression induces resistance to multiple cancer drugs through TGF-βR signaling regulation." (PMID 27602765, 2016). "MED12 was recently found to inactivate TGFβR signaling and control response to several drugs in different cancer models." (PMID 25277175, 2014). "In addition, we knocked down TAP2 and MED12 in cancer cells, and then co-cultured these cancer cells with CD8 + T cells, and quantified lactate dehydrogenase (LDH) levels to assay T cell cytotoxicity, as a consequence of antigen processing and presentation." (PMID 40888963, 2025). "Targeting the MED12 signaling pathway holds promise as a novel strategy to combat drug-resistant cancers, and understanding the specific roles of MED12 in different cancer subtypes is crucial for developing personalized treatment approaches and improving patient outcomes." (PMID 40833497, 2025). "Although further investigation is required to clarify the direct regulatory relationship between MED12 and MYC, our results suggest that functional loss of MED12 attenuates AKT-mediated survival signaling, thereby increasing the vulnerability of cancer cells to MEK inhibition." (PMID 40833497, 2025). "MED12 gene is noted to have copy number alterations or somatic mutations, or aberrant expressions in various cancers, but the prognostic significance of these changes is not clear." (PMID 38467827, 2024).
cancer (continued). "This could indicate a compensatory mechanism of the cells or suggest that MED12 might play a dual role depending on the cancer stage." (PMID 39253786, 2024). "Overall the genomic landscape was stable, with pathogenic or likely pathogenic alterations being identified in 51 cancer genes, with 9 (18%) of them showing alterations being recurrent across different samples (MYCN, CDKN2A/2B, CDK4, GLI1, AKT1, IGF2, MED12, NCOR2)." (PMID 37730754, 2023). "Totally, MED12-Mut successfully predicted better clinical outcomes in ICIs-treated pan-cancer cohort, indicating that MED12-Mut could serve as a potential predictive biomarker for immune checkpoint inhibitors in pan-cancer." (PMID 36309740, 2022). "Mediator complex subunit 12 (MED12) is an essential hub for transcriptional regulation, in which mutations and overexpression were reported to be associated with several kinds of malignancies." (PMID 31072327, 2019). "Whether MED12 has the similar function in other cancer cells is currently under investigation by our laboratory." (PMID 31072327, 2019). "Further, loss of MED12 was shown to induce a mesenchymal phenotype through activation of TGF-β signaling and thereby epithelial-mesenchymal transition (EMT), which is known to contribute in cancer progression and metastatic spread." (PMID 27050271, 2016). "Thus, we suspect that MED12 may regulate the expression of transcription factors and subsequently modulate expression of APGs in cancer cells." (PMID 40888963, 2025). "Similarly, oncogenic mutations in the cancer driver gene MED12 previously had no structural data at all, but are now covered by a high-confidence model." (PMID 35073311, 2022). "Besides, mediator complex subunit 12 (MED12) is an essential hub for transcriptional regulation, in which mutations and overexpression were reported to be associated with several kinds of malignancies." (PMID 35071776, 2022). "We next examined whether MED12 may regulate cancer cell proliferation." (PMID 31072327, 2019). "Whilst PTs with FA-like areas harbor highly recurrent MED12 exon 2 mutations and less common genetic alterations in bona fide cancer genes, most PTs without FA-like areas are MED12-wild-type and display more frequent genetic alterations targeting cancer genes, in particular EGFR." (PMID 29043292, 2017). "Furthermore, MED12 and BRD4 could cooperate to sustain cancer growth upon loss of mediator kinase." (PMID 37488513, 2023). "The close relationship between tumorigenesis among multiple cancer types and numerous mediator complex subunits including MED1, MED12, MED16, and MED19 has been extensively reported." (PMID 35558516, 2022). "By contrast, in the MED12-wild type pathway, borderline and malignant PTs are more likely to develop de novo, and driven by early genetic alterations in TERT and/or other cancer genes." (PMID 29043292, 2017). "Notable cancer genes with high fractions of hypomutated positions include PIM1 and MED12, with respectively 34% and 32% of their non-coding length that is hypomutated." (PMID 26588488, 2015). "Due to its role in essential developmental and cell fate determination processes, it is not surprising that MED12 deregulation can lead to cancer." (PMID 35326717, 2022). "Different expression and activation levels of GLI3-FL regulators (SPOP, androgen receptor, PP2A, CBP, SET7, MED12) or regulators of GLI3-R (PKA, GSK3β, βTrCP) in cancer cells in comparison to healthy cells might also promote cancer cell growth and survival." (PMID 32245491, 2020). "MED12 is significantly associated with survival in completely independent immunotherapy datasets, including MSKCC (N = 350), Naiyer2015 (N = 34), our own (N = 295) and the pan-cancer dataset, but not in the TCGA dataset, where patients received non-immunotherapy regimens." (PMID 40888963, 2025).
benign tumors (6 papers, 2012 to 2025). "Genomic driver alterations are identifiable in many benign neoplasms; for instance, uterine leiomyomas harbor recurrent MED12 mutations as well as complex chromosomal rearrangements, and profiling of hepatocellular adenomas has revealed multiple recurrent mutations." (PMID 32332823, 2020).
genetic disorders (6 papers, 2013 to 2023). "One potential example of fetal ethanol exposure influencing the prognosis of a genetic disorder is Opitz-Kaveggia syndrome, an X-linked mental retardation disorder resulting from mutations in MED12." (PMID 23342055, 2013). "Genetic disorders associated with mutations in the MED12 gene provide an interesting example." (PMID 23342055, 2013).
neurodevelopmental disorder (3 papers, 2016 to 2021). A behavioral and cognitive disorder with onset during the developmental period that involves impaired or aberrant development of intellectual, motor, or social functions. "A previous study reported that variants in MED12 and MED13L were associated with neurodevelopmental disorders." (PMID 33748132, 2021). "Four of the identified genes (CUL4B, HDAC8, MED12, and USP9X) have been previously reported to harbor de novo PTVs and Dmis variants in male cases with neurodevelopmental disorders, providing more genetic evidence of their pathogenicity." (PMID 33023636, 2020). "Med12 may thus contribute to the regulatory apparatus that controls the balance between NSC self-renewal and differentiation, with important implications for MED12-linked neurodevelopmental disorders." (PMID 27188461, 2016).
bacterial infection (1 paper, 2015). "Interestingly, MED12 has been found to be significantly upregulated upon MTB infection of DCs, suggesting a role of this gene in the regulation of this miRNA cluster in response to bacterial infection." (PMID 25793259, 2015).
MED12 also shares sentences with these, for which no sentence is quoted: melanoma (5 papers); intellectual disability syndromes (3); 22q11.2 deletion syndrome (2); endometriosis (2); Kabuki syndrome (2); lipoleiomyomas (2); renal cell carcinoma (2); Rett syndrome (2); Smith-Magenis syndrome (2); thyroid cancer (2); adenomyosis (1); aneurysm (1); Angelman syndrome (1); angioleiomyoma (1); Aortic Valve Disease 1 (1); B-cell acute lymphoblastic leukemia (1); Bannayan-Riley-Ruvalcaba syndrome (1); benign phyllodes tumor (1); benign prostatic hyperplasia (1); benign uterine neoplasms (1); CHARGE syndrome (1); chlamydia infection (1); congenital malformations (1); Cornelia de Lange syndrome (1); Cowden syndrome (1); diabetes (1); endometrial polyp (1); epilepsy (1); FG syndrome 1 (1); Floating-Harbor syndrome (1).
A further 35 diseases each share a sentence with MED12 in 1 paper.